IL3 (interleukin 3)
Diseases named in the same sentence as IL3 in open-access papers (continued):
Sharing a sentence is not in itself a finding about the gene and the disease.
asthma (continued). "Their research underscores the potential role of IL-3 not in the acute phase of respiratory infections as a biomarker for the risk of chronic inflammatory airway diseases, such as asthma." (PMID 40872787, 2025). "However, this pro-inflammatory role of IL-3 has also been challenged, since in asthmatic children, a direct correlation was observed between blood IL-3 levels and an improved lung function, thereby supporting the resolution of asthma." (PMID 37275910, 2023). "However, by looking closely at their clinical data, we found that the child with no IL-3 in the NPF had worse lung function and higher C-reactive protein (CRP), confirming a possible role of IL-3 in the amelioration of asthma." (PMID 35281014, 2022). "We also had 3 children with uncontrolled asthma who had scattered levels of IL-3 in the NPF." (PMID 35281014, 2022). "In addition, we analyzed children treated with steroids with controlled and partially controlled asthma and found that IL-3 was induced in this group." (PMID 35281014, 2022). "Moreover, IL-3 was found induced in phytohemagglutinin (PHA)-stimulated PBMCs from children with asthma and treated with steroids." (PMID 35281014, 2022). "Furthermore, the authors found a correlation between high levels of IL-3 with episodes of recurring wheezing and the development of asthma in the future." (PMID 31214165, 2019). "By combining our previous in vitro data and current in vivo observations, we speculate that circulating basophils from stable asthma patients are in continuous and prolonged exposure to IL-3, secreted by activated T cells, mast cells, or basophils, ultimately resulting in the upregulation of CD25." (PMID 36685514, 2022). "However, it is unknown if ILC2s are influenced by IL-3 via IL-3R expression, in general, and in asthma, in particular." (PMID 35281014, 2022). "Moreover, although IL-3 was found in the bronchial airways of both asthmatic and control subjects after the allergen challenge, its increase did not correlate with airway hyperresponsiveness, metacromasia or eosinophil activation in allergen-induced asthma." (PMID 35281014, 2022). "Thus, the role of IL-3 in asthma needs further investigation." (PMID 35281014, 2022). "To analyze the link between IL-3, ILC2, and the amelioration of asthma, we reasoned that IL-3 might be involved in the regulation of the inflammatory and anti-inflammatory properties of ILC2 via the regulation of the anti-inflammatory form of ST2 known as sST2." (PMID 35281014, 2022). "In patients with mild to moderate asthma, basophils were strongly activated by TSLP leading to secondary production of IL-3, suggesting that in certain contexts TSLP and IL-3 can also act in concert." (PMID 36846020, 2022). "Asthma pathogenesis primarily involves activation of eosinophils and CD4+ T cells, with downstream inflammation mediated mainly by Th2-type cytokines (IL-3, IL-4, IL-5, IL-9, IL-13, and granulocyte macrophage colony-stimulating factor)." (PMID 30126769, 2019). "“Immune System” was a heterogenous group of molecular processes such as dendritic cell chemotaxis and cytokine production, IL-1, IL-3, IL-4, TLR and PD-1 signaling, asthma-related signaling and activation of RAS GTPase in B-cells." (PMID 31597351, 2019). "In a cohort of preschool children with and without asthma, we analyzed the secretion of IL-3 in nasopharyngeal fluid (NPF) and IL-3 receptor (R) alpha chain mRNA expression in peripheral blood mononuclear cells (PBMCs)." (PMID 35281014, 2022). "Our study results revealed that IL-5 and GM-CSF, but not IL-3, exhibited a significant effect on the proliferative properties of eosinophil subtypes in asthma patients." (PMID 36497064, 2022). "The cytokine IL-3 is known to support eosinophil, basophil and mucosal mast cell differentiation and survival; however, its role on T regulatory cells as well as on lung ILC2 and in pediatric asthma needs further investigation." (PMID 35281014, 2022).
asthma (continued). "IL-36, IL-38, and IL-3 are believed to be new members of the IL-1 family and are involved in the pathogenesis of asthma, and hypermethylation of IL1R2 (2q11.2) in blood shows asthma-related phenotypes." (PMID 34566492, 2021). "While asthma involved pathways like NFAT in regulation of the immune response and other lymphocyte activation pathways including signaling through IL-4, IL-8, IL-3 and IL-9 in CD8+ cells, the most prominent pathway in CD4+ cells was VDR/RXR activation signaling." (PMID 32900903, 2020). "CCL15 protein production was observed when basophils isolated from the peripheral blood of asthma patients and nonasthmatic control subjects were stimulated with IL-3." (PMID 23258953, 2012). "To investigate this hypothesis, we analyzed the secretion of IL-3 in preschool children with and without asthma, correlated its regulation in different asthma phenotypes and treatment, and studied wild-type (WT) mice treated with recombinant IL-3 in an experimental model of allergic asthma." (PMID 35281014, 2022).
COVID-19 (30 papers, 2021 to 2025). A disease caused by infection with severe acute respiratory syndrome coronavirus 2. "Of note, low levels of IL-3 in the circulation of COVID-19 patients is associated with enhanced severity of the disease and mortality." (PMID 35280992, 2022). "In severe COVID-19, elevated IL-3 and IL-33 in the lung microenvironment suggest a shift toward innate “alarmin” driven, type-2 inflammation." (PMID 41459501, 2025). "IL3 expression was significantly higher in patients with severe COVID-19 compared to both healthy controls and mild cases." (PMID 41459501, 2025). "For the IgG autoantibodies, the severe COVID-19 group trended for higher levels in many of the analytes tested and had statistically significant higher levels of both IL-3 and IFNα2 cytokines (p ≤ 0.05; Wilcoxon–Mann–Whitney)." (PMID 38491326, 2024). "Several studies showed a significant increase in inflammatory cytokines, such as IL-3, IL-6 and IL-10, among patients with a severe or lethal disease course of COVID-19." (PMID 36769623, 2023). "Accordingly, several interleukins (e.g., IL-3, IL-6 or IL-10) have been identified as predictors of adverse events and higher mortality in COVID-19." (PMID 36769623, 2023). "It is also important to note that IL-3, which is mainly produced by T cells is an essential survival factor for pDCs and is also depleted in COVID-19." (PMID 36142877, 2022). "The average IL-6 concentration was higher in patients with COVID-19 than in normal controls, whereas IL-3 showed the opposite behavior." (PMID 36129990, 2022). "During the first wave of the COVID-19 pandemic, IL-3 was suggested as one of the potential markers of severity." (PMID 36430621, 2022). "Specifically, in severe COVID-19 participants, IL-3 was detected at very high levels in the nasal lining fluid, while Flt-3L was repressed in serum." (PMID 34117221, 2021). "In conclusion, the study hypothesized that pioglitazone could impact COVID-19-infected patients by reducing inflammatory markers such as IL-3 and CRP." (PMID 39308871, 2024). "In addition, in the BALF of COVID-19 patients with pulmonary manifestation a positive correlation was found between IL-3 and CXCL12 levels." (PMID 36142877, 2022). "Measuring IL-3 and IL-6 in patients with COVID-19 produced intriguing results." (PMID 36129990, 2022). "Notably, IL-3 in patients with COVID-19 was difficult to quantify by ELISA because IL-3 concentration in this cohort (7 pg/ml ~ 0.4 pM, on average) was close to or below ELISA’s quantification limit." (PMID 36129990, 2022). "We lastly applied ECLipse to analyze IL-3 and IL-6 in plasma samples of patients with COVID-19." (PMID 36129990, 2022). "ECLipse, in contrast, could reliably resolve low IL-3 levels, revealing robust differences in IL-3 concentration between patients with COVID-19 and normal controls." (PMID 36129990, 2022). "Severe COVID-19 patients display low IL-3 in the circulation that could be responsible for the reduced expression of PD-L1 in basophils reported in one study." (PMID 35269423, 2022). "In addition, IL-3 levels were distinctively high in nasal lining fluid and serum of PCR-confirmed COVID-19 and PCR−/IgG+ SARI participants, relative to healthy controls." (PMID 34117221, 2021). "We have found fifteen cytokines that remain upregulated in convalescent COVID-19 individuals one month after infection (IL-1α, IL-3, IL-10, IL-12p70, CCL7, IFN-α2, bFGF, LIF, TRAIL, IL-2, IL-4, IL-5, IL-12p40, IL-17 and MIF) indicating a strong activation of the immune response." (PMID 34681885, 2021). "Thus, we hypothesize that IL-6 upregulation in COVID-19, as well as IL-3 and IL-11 upregulation, is likely involved in the stimulation of megakaryocytes and possibly also resident megakaryocytes in the lung." (PMID 38786077, 2024). "Therefore, it is plausible that high levels of IL-3 and repressed levels of Flt-3L could contribute to the high neutrophil to lymphocyte ratio and altered leucocyte numbers observed in severe COVID-19 patients." (PMID 34117221, 2021).
COVID-19 (continued). "None of the other measured mediators related to eosinophils and the T2 response (CCL26, IL-3, IL-4, IL-5, CD44, TSLP, or GM-CSF) displayed any significant differences between the different timepoints and between COVID-19 versus controls." (PMID 40710346, 2025). "Six chemokines (CXCL9, CXCL10, CCL4, CCL5, CCL27, and CXCL12) and eight interleukins (IL-1Ra, IL-2Ra, IL-3, IL-5, IL-9, IL-12p40, IL-15, and IL-16) were increased in both PLWH/COVID-19 and COVID-19-only." (PMID 41516165, 2025). "Given that IL-33 was responsible for the enhanced expression of CD25 and CD132 on IL-3–primed basophils in our in-vitro experiments, we next evaluated the expression of IL3 and IL33 in BALF cells from COVID-19 patients." (PMID 41459501, 2025). "In parallel, we observed a similar expression pattern of IL-2 receptors in COVID-19 patients, where basophils from severe cases showed upregulation of CD25 and CD132, but not CD122, a profile that correlated with elevated levels of IL-3 and IL-33." (PMID 41459501, 2025). "Higher levels of IL-3 and IL-33 cytokines in inflammatory environments explain the higher levels of CD25 expression in allergic patients, as well as in severe COVID-19 patients." (PMID 41459501, 2025). "Together, these findings suggest that IL3 and IL33 contribute to the upregulation of IL2RA and IL2RG on basophils in severe COVID-19." (PMID 41459501, 2025). "Another interesting finding was the increased serum levels of IL-1β, IL-3, IL-17, and CCL3 in severe COVID-19 exclusively." (PMID 37373331, 2023). "We first observed a significantly elevated level of 7 serum cytokines (IL-1Ra, IL-2, IL-3, IL-10, IL-12p40, CXCL10, and HGF) in all COVID-19 cases when compared with controls." (PMID 35386707, 2022). "To interrogate the potential role of T cell activation–related biomarkers in COVID-19 immunopathogenesis, we measured levels of IL-2, sCD25 (or sIL-2Rα), soluble CD40 ligand (sCD40LG), soluble FAS ligand (sFASLG), IL-7, and IL-3." (PMID 33232303, 2021). "A set of cytokines were upregulated in SputnikV immunized individuals (IL-1α, IL-3, IL-10, IL-12p70, CCL7, IFN-α2, bFGF, LIF and TRAIL), where nine of them were similar to that in convalescent COVID-19." (PMID 34681885, 2021). "The almost complete inhibition of cytokine release from activated T cells in ventilated COVID-19 patients strongly suggests that both CD4 + and CD8 + T cells are hyporeactive, as IL-3 and IFN-gamma are released from both, CD4 + and CD8 + T cells." (PMID 34021143, 2021). "However, some cytokines, including IL-1β, IL-3, IL-17, and CCL3, were uniquely activated in severe COVID-19." (PMID 37373331, 2023). "The ratios of the serum concentrations of IL-3, GM-CSF and G-CSF were increased in the survivors compared to the non-surviving severe COVID-19 patients." (PMID 36142255, 2022). "Based on our data, we suggest that a combination of IL-3 and IFN-γ could be responsible for the enhanced expression of PD-L1 in basophils of recovered COVID-19 patients." (PMID 35269423, 2022). "Several mediators such as Tie-2, VEGFA, IL-17D, IL-3, GM-CSF, IL-1α, IL-5, Eotaxin 3, IL-12p70 and IL-13 were not significantly different between COVID-19 and control subjects (data not shown)." (PMID 36116160, 2022). "Patients with COVID-19 showed lower IL-3 and higher IL-6 concentrations in plasma than noninfected controls." (PMID 36129990, 2022). "Here, the authors identify interleukin-3 as a predictive marker for severity and outcome of SARS-CoV-2 infection in a multi-center, prospective study and find that patients with severe COVID-19 have reduced circulating plasmacytoid dendritic cell levels compared to non-severe COVID-19 patients." (PMID 33602937, 2021). "Interestingly, in our study, concentrations of IL-3 and Flt-3L were distinctively altered in severe COVID-19 participants compared to non-COVID-19 SARI participants." (PMID 34117221, 2021).
COVID-19 (continued). "However, we did not observe similar results in COVID-19, as we reported an inverse correlation between IL-3 levels and SOFA scores." (PMID 34616409, 2021). "We investigated the circulating levels of the G-CSF, GM-CSF, M-CSF, IL-3, IL-7, FLT3L and IL-2 growth factors and soluble receptor sIL2Ra in the surviving and non-surviving severe COVID-19 patients and healthy controls." (PMID 36142255, 2022). "We found no significant anti-CD3-induced release of IL-3, GM-CSF, and IFN-gamma in ventilated COVID-19 patients, but a considerable release in non-ventilated patients and healthy controls." (PMID 34021143, 2021). "Mechanistically, IL-3 increases innate antiviral immunity by promoting the recruitment of circulating pDCs into the airways by stimulating CXCL12 secretion from pulmonary CD123+ epithelial cells, both, in mice and in COVID-19 negative patients exhibiting pulmonary diseases." (PMID 33602937, 2021).
eosinophilia (27 papers, 2009 to 2025). "Most eosinophilia is reactive, caused by an overproduction of eosinophilopoietic cytokines such as interleukin 3 (IL-3), interleukin 5 (IL-5), or granulocyte-macrophage colony stimulating-factor (GM-CSF)." (PMID 40567444, 2025). "Second, we did not measure the markers that influenced eosinophil activity, such as IL-3, IL-5, and GM-CSF, and were unable to identify the association between eosinophilia and the extent of eosinophilic inflammation." (PMID 32266635, 2020). "It is not uncommon for nonmyeloid malignancies such as T-cell lymphomas and Hodgkin's disease to be associated with secondary eosinophilia due to the production of cytokines such as IL-3, IL-5, and GM-CSF which promote eosinophil differentiation and survival." (PMID 24224106, 2013). "The ectopic mRNA expression of IL3 may be the main cause of eosinophilia, and HU and prednisone acetate (PAT), as well as IFN, were considered treatments for this group." (PMID 35747804, 2022). "Typically, it is believed that the eosinophilia is caused by the production of various cytokines, such as interleukin (IL)-5, IL-3, and granulocyte–macrophage colony–stimulating factor (GM-CSF) by B cell lymphoma cells or non-neoplastic T lymphocytes activated by B cell lymphoma cells." (PMID 25273521, 2014). "It is known that IgE and IgG4 responses are elicited by IL-4, while IFN-γ and eosinophilia are stimulated through IL-3 and IL-5." (PMID 40041800, 2025). "In a mouse model of allergic airways inflammation, allergen-induced lung tissue eosinophilia was abolished in mice bred to lack the common β-subunit, therefore incapable of responding to IL-3, IL-5, and GM-CSF." (PMID 28713812, 2017). "Inhibition of GM-CSF/IL-3/IL-5 signaling by ASOs targeting the βc of their receptors or CCR3 expression in vivo suppressed antigen-induced eosinophilia and AHR in rat models of allergic asthma." (PMID 28106744, 2017). "IL-3 and IL-5 play a crucial role in the growth, differentiation, and activation of eosinophilia." (PMID 39873807, 2025). "IL-3 binds to its receptor, IL-3 receptor subunit alpha (IL-3Rα), on eosinophils, triggering intracellular signaling pathways that enhance protein production and prolong cell survival, ultimately leading to eosinophilia." (PMID 39873807, 2025). "In addition to IL-5, cytokine IL-3 and GM-CSF have also been shown to mediate airway eosinophilia and AHR." (PMID 28106744, 2017). "In addition to the eosinophil chemotactic factors IL-3 and GM-CSF, IL-5 is a major soluble factor for mediating eosinophilia." (PMID 25273521, 2014). "However, some authors hypothesized a shared immune dysregulation and neoantigen-induced T-cell response with type 2 skewing (e.g., IL-3/5 cytokines, eosinophilia)." (PMID 37760419, 2023). "The residual tissue eosinophilia may reflect ongoing effects mediated by IL-3 and GM-CSF." (PMID 28713812, 2017). "In L-HES, eosinophilia is considered a reactive phenomenon secondary to the overproduction of eosinophilopoietic cytokines such as interleukin-5 (IL-5) and/or IL-3 by clonal T-cells, rather than a primary myeloid process." (PMID 41488087, 2025). "However, several other inflammatory pathways have been shown to support eosinophilia, including IL-13, the alarmin cytokines TSLP and IL-33, and the IL-3/5/GM-CSF axis." (PMID 33917396, 2021). "Second, we did not evaluate other molecules that contribute to eosinophilia, such as IL‐2, IL‐3, IL‐5, GM‐CSF, and NKG2D." (PMID 31950647, 2020). "Typically, the host immune response to helminth infection is characterized by the T helper 2 (Th2) response, which involves the production of cytokines interleukin 3 (IL3), IL4, IL5, IL9, and IL13, eosinophilia, goblet, and mast cell hyperplasia, as well as alternatively activated macrophages." (PMID 30245697, 2018).
eosinophilia (continued). "Increased expression of IL-3 protein transcript has been documented in two ETV6-ACSL6 cases and dysregulation of the IL-3 gene due to a translocation event has been hypothesized as a mechanism for eosinophilia." (PMID 27746819, 2016). "Finally, although some authors have reported elevated IL-3 in the plasma of patients with eosinophilia in conjunction with intracellular staining in CD8+ T cells, IL-3 is not universally detected in serum of patients with HES, and the role of IL-3 as a biomarker in HES remains to be explored." (PMID 29312946, 2017).